KRAS (KRas proto-oncogene, GTPase)
Diseases named in the same sentence as KRAS in open-access papers (continued):
Sharing a sentence is not in itself a finding about the gene and the disease.
pancreatic cancer (continued). "KRAS-4B is the dominant isoform relative to KRAS-4A in human cancers, and it is present in approximately 90% of pancreatic cancers, 30–40% of colon cancers, and 15–20% of lung cancers, mostly NSCLCs5." (PMID 37779142, 2023). "In pancreatic cancer, the role of RAD51 in PDAC cell proliferation and cancer development has rarely been described, although KRAS mutation has been reported to increase RAD51 expression." (PMID 36262061, 2023). "One potential anti-KRAS strategy is targeting pancreatic cancer cell dependence on proteostasis, or protein homeostasis, which maintains balance between protein translation and degradation." (PMID 36923647, 2023). "As expected, we confirmed the degradation and apoptosis of KRAS G12D and G12V in colon cancer cells and pancreatic cancer cells, respectively." (PMID 37513471, 2023). "When injected intravenously into mice bearing pancreatic tumors, the treatment using LNPs in combination with gemcitabine resulted in reduced tumor size and the downregulation of KRAS and phospho-ERK." (PMID 38069255, 2023). "KRAS, which has previously been identified as one of the major drivers of pancreatic cancer, upregulates the activities of NRF2-dependent chemoresistance." (PMID 36975494, 2023). "Mutant KRAS (muKRAS) has been identified as a driver gene in human pancreatic cancer and is identified in about 90% of those with this tumor." (PMID 36614194, 2023). "The association between glutamine deprivation, NRF2/KEAP1, and cytokine secretion in KRAS-mutant pancreatic cancer warrants further investigation." (PMID 36942991, 2023). "Other recent studies have indicated that KRAS-wild type pancreatic cancer has various targetable alterations." (PMID 37046493, 2023). "Gain-of-function KRAS mutations that lead to constitutive activation of the MAPK pathway play a critical role in the initiation and maintenance of pancreatic cancer (frequency about 65%), highlighting this pathway as a pharmacological target in this disease." (PMID 37568682, 2023). "Of the three major RAS-family isoforms, mutated KRAS comprises 84% of all RAS-driven diseases and propagates many aggressive tumor types, including lung, colorectal, and pancreatic cancer." (PMID 37141389, 2023). "In spite of targeting RAS itself, a dual FT and geranylgeranyltransferase‐1 inhibitor named FGTI‐2734 can inhibit the growth of xenografts derived from four patients with pancreatic cancer with mutant KRAS (two G12D and two G12V) tumors." (PMID 37250144, 2023). "Similar to ARID1A, the inactivation of RNF43 in combination with KRAS activation in the pancreas of mice significantly increased the incidence of high‐grade cystic lesions and pancreatic cancer." (PMID 36999792, 2023). "Notability, mutant KRAS enhanced the specific AA intake process named macropinocytosis in pancreatic cancer, resulting in maintaining the AA supply and thus promoting tumor progression." (PMID 37333498, 2023). "The expression of VMP1 in pancreatic cancer stem cells carrying the activated Kirsten rat sarcoma viral oncogene homolog (KRAS) triggers autophagy and enables therapy resistance." (PMID 37629161, 2023).
pancreatic cancer (continued). "The encapsulation of irinotecan into lipid bilayer-coated mesoporous silica nanoparticles (silicasome) led to an improvement of the delivery and therapeutic efficacy both in vitro and in vivo in KRAS-induced pancreatic cancer cell models." (PMID 37376135, 2023). "In this study, KRAS genotyping by dPCR combined with melting curve analysis was applied to ctDNA extracted from the plasma of pancreatic cancer patients." (PMID 36810451, 2023). "We next examined the effects of KRB-456 on the levels of KRAS bound to GTP and on the binding of KRAS to RAF1 in intact Panc0203 and Panc1 human pancreatic cancer cells that harbor mt KRAS G12D." (PMID 38051103, 2023). "This counterintuitive result is now tested in a clinical trial of KRAS G12D pancreatic cancer (NCT05068752)." (PMID 36607281, 2023). "One of the main factors impeding the delivery of drugs is mucin, which has been found to be overexpressed in KRAS-driven pancreatic cancer in mice and human models." (PMID 36975494, 2023). "Pancreatic cancer cells succumbing to ferroptosis release KRAS mutant proteins for packaging into exosomes that are taken up by macrophages." (PMID 36670112, 2023). "This is of particular importance because experiments in mice have shown that relapsed KRAS pancreatic tumours have activated YAP1/TEAD2 transcriptional programs that are required for tumour growth." (PMID 36175301, 2023). "This discovery opens new avenues to target KRAS G12D- and KRAS G12V-driven pancreatic cancer, and as such it warrants further advanced preclinical and clinical studies." (PMID 38051103, 2023). "In a phase 1 trial, ELI-002 was administered via subcutaneous injection as an adjuvant treatment of minimal residual disease in 22 patients with KRAS/NRAS mutant pancreatic cancer (NCT05726864)." (PMID 38069255, 2023). "Oncogenic KRAS has also been shown to induce GM-CSF in pancreatic cancer, resulting in the expansion of immunosuppressive Gr1+CD11b+ myeloid cells and inhibition of T-cell–mediated tumor control." (PMID 37581538, 2023). "We also demonstrated that OBP-301 and OBP-702 induce autophagy-related death in KRAS-mutant human pancreatic cancer cells by suppressing the KRAS signaling pathway." (PMID 37972012, 2023). "Here, we report on the discovery of a small molecule, KRB-456, that binds KRAS G12D and inhibits the growth of pancreatic cancer patient-derived tumors." (PMID 38051103, 2023). "For example, MSC-derived EVs transfected with miR-124 have been used to treat ischemic stroke (NCT03384433), and MSC-derived EVs loaded with miRNA against mutant KRAS have been used to treat pancreatic cancer (NCT03608631)." (PMID 36986843, 2023). "Compared with KC mice, KCR mice exhibited a significant reduction in the formation of PanIN lesions of all grades (IA, IB, II, III) at both 6 and 9 months of age, suggesting RASON is involved in the early stage of KRAS-driven pancreatic tumor initiation." (PMID 36241718, 2023). "Enzymes responsible for the biosynthesis of GM3 are essential for activated KRAS signaling and for KRAS oncogenesis in mouse models of pancreatic cancer." (PMID 36709325, 2023). "From the discovery of the first oncogene SRC to the later oncogenes EGFR, NRAS/KRAS, and the presence of mutant KRAS fragments in the plasma of pancreatic cancer patients, these oncogenes have proved the real ctDNA for the first time." (PMID 36757457, 2023).
pancreatic cancer (continued). "Overall, the cell proliferation inhibition was observed quite similarly for siR-KRAS and MIR143 towards pancreatic cancer KRAS mutant cells." (PMID 37371705, 2023). "The Bhatia group reported the use of a “tandem peptide “construct containing the myristoylated transportan fused to a PEG spacer with a C-terminal targeting peptide, iRGD (cyclic peptide of CRGDKGPDC), for pancreatic tumor delivery of anti-KRAS (WT) siRNA." (PMID 37298407, 2023). "We transplanted MIA PaCa-2 cancer cells, a KRAS-mutant pancreatic cancer cell line most vulnerable to ARL-17477, subcutaneously into the tissue of nude mice." (PMID 37402770, 2023). "GPC1-enriched tumor exosomes contain mutant KRAS mRNA and have been indicated as a reliable biomarker for the detection of early pancreatic cancer." (PMID 36835443, 2023). "RAS is a crucial driver of effector pathways, and its oncogenic activation is frequently found in pancreatic cancer, particularly in the KRAS isoform." (PMID 37371705, 2023). "In an in vivo study, the CRISPR-Cas13a system targeting KRAS G12D was injected intratumorally into mice bearing pancreatic tumor xenografts." (PMID 38069255, 2023). "A low LIFR expression was associated with shorter survival in pancreatic cancer and NSCLC patients with mutated KRAS." (PMID 36793597, 2023). "KRAS and BRAF mutations are other two mutations widely assessed in various cancer types, including pancreatic cancer, colon cancer, and melanoma." (PMID 37849806, 2023). "In pancreatic cancer, LXA4 is associated with attenuated cancer cell invasion and metastasis by inhibiting KRAS-induced ROS production, as well as ERK/MMPs and TGF-β1 signaling pathways." (PMID 36675307, 2023). "Quantitative RT-PCR analysis demonstrated lower KRAS G12D mRNA expression in these three PDTO compared to KRAS G12D/A*11:01-expressing pancreatic cancer cell lines known to be recognized by the KRAS G12D/A*11:01-restricted TCR." (PMID 37368077, 2023). "This interaction was considered important for tumorigenesis of pancreatic cancer, i.e., loss of EFR3A inhibited KRAS signaling and cancer progression." (PMID 37880612, 2023). "When combined with KRAS activation, loss of ARID1A in the pancreas accelerated the formation of intraductal pancreatic mucinous neoplasms (IPMNs) and pancreatic cancer." (PMID 36999792, 2023). "Studies have shown that LFNG deficiency accelerates KRAS-induced pancreatic cancer development in mice, while LFNG expression inhibition suppresses pancreatic cancer cell proliferation and migration by inhibiting NOTCH1 activation." (PMID 37932706, 2023). "Reciprocally oncogenic KRAS selectively upregulates cellular content of these same glycosphingolipids, whose depletion in turn abrogates KRAS oncogenesis in pancreatic cancer models." (PMID 36709325, 2023). "Therapeutically, deprivation of RASON sensitizes KRAS mutant pancreatic cancer cells and patient-derived organoids to EGFR inhibitors." (PMID 36241718, 2023). "In pancreatic cancer, reporting on KRAS, as a direct correlate of VTE is relatively scarce, despite both being generally prevalent in this disease setting." (PMID 38188342, 2023). "Tested across a range of colorectal, lung, skin, and pancreatic cancer cell lines in vitro, BI-3406 displays KRAS-mutant cancer specific activity, capable of inducing apoptosis through MAPK inhibition." (PMID 37190303, 2023). "Aside from KRAS, oncogenic mutations in other RAS/RAF/MAPK pathway genes also can drive pancreatic cancer." (PMID 36999792, 2023). "On this basis, we have proposed a combined panel of EV-packaged biomarkers for pancreatic cancer with different KRAS subtypes, to provide an alternative strategy for more accurate monitoring of LN metastasis in early stages." (PMID 36971125, 2023).
pancreatic cancer (continued). "The expression of NOP56 in KRAS mutant pancreatic cancer cell lines (MIAPaCa, HPAF-II) and colon cancer cell lines (HCT-116, DLD-1) is significantly higher than that in KRAS wild-type tumor cell lines." (PMID 36741964, 2023). "In pancreatic cancer, wild type KRAS was targeted with siRNA(unmodified)-p5RHH polyplexes administered systemically in serial doses to subcutaneous KPC-1 PDAC xenografts." (PMID 37298407, 2023). "In most human pancreatic cancers a transition in the 12th codon of KRAS occurs with a change from GGU in the sense strand of the wild type KRAS mRNA to GAU in the mutant sense mRNA." (PMID 36614194, 2023). "RAS (KRAS, NRAS, and HRAS) is the most frequently mutated gene family in cancers, especially lung, colorectal, and pancreatic cancers." (PMID 36817861, 2023). "Multivariable‐adjusted associations of CDK7 expression with overall survival (OS) and disease‐free survival (DFS) after excluding cases who died within 3 months after resection in our resected pancreatic cancer cohort, stratified by KRAS." (PMID 38037549, 2023). "Pancreatic cancer (PDAC) is driven by mutant KRAS that feeds to PI3K-AKT-mTOR signaling to support anabolic pathways and cancer cell growth." (PMID 36900235, 2023). "Subsequently, the M1 macrophages secreted TNF and matrix metalloproteinase-9 (MMP-9), which cooperated with KRAS signaling to accelerate the pathogenesis of pancreatic cancer." (PMID 37670322, 2023). "The results of the present study show that the abnormal activation of KRAS induced the overexpression of ITGA2 in pancreatic cancer." (PMID 35193647, 2022). "To investigate the potential cause for these significant alterations in the sensitivity to MEKi, we carried out unsupervised hierarchical clustering of 11 KRAS-mutant pancreatic cancer cell lines from the Cancer Cell Line Encyclopedia (CCLE)." (PMID 35806187, 2022). "Initial experiments were performed in pancreatic cancer (PC) cell lines AsPC1 and HPAF/CD18, both carrying an oncogenic mutation in the KRAS gene." (PMID 35114566, 2022). "Our in vivo testing of KRAS(G12D) inhibitors was conducted in two xenograft pancreatic tumor models: BALB/c nude mice subcutaneously inoculated with Panc 04.03 cells and C57BL/6 mice inoculated with KPC cells." (PMID 35075146, 2022). "Coexistence of mutated RNF43 and KRAS in PDAC also supports a collaboration between RNF43 and KRAS in the development of human pancreatic cancer." (PMID 35229994, 2022). "To better investigate how MYEOV, GPRC5A, and KRAS act together in pancreatic cancer, we utilized the String database, a dedicated database for studying protein interaction networks." (PMID 36358856, 2022). "AHNAK2, ARL4C, ASAP2, SEMA3C were identified as being highly expressed in both KRAS G12D cell lines and pancreatic cancer patients." (PMID 35785187, 2022). "Matrine inhibits KRAS mutant pancreatic cancer growth by inhibiting autophagy-mediated energy metabolism and mitochondrial energy production." (PMID 35847371, 2022). "KRAS-transformed pancreatic cancer cells activate macropinocytosis to absorb and degrade extracellular fluids in order to survive." (PMID 36046825, 2022). "To identify mechanisms of resistance to MEK inhibitor (MEKi), we employed a differential expression analysis of MEKi-sensitive versus MEKi-resistant KRAS-mutant pancreatic cancer cell lines." (PMID 35806187, 2022). "Wild‐type KRAS were detected for all patients, and the higher copy numbers of total KRAS transcripts were used to differentiate pancreatic cancer from healthy donor and monitor the disease progression of pancreatic cancer." (PMID 35486030, 2022).
pancreatic cancer (continued). "Upon adagrasib treatment, the KRAS Y96D mutation was associated with sustained ERK and AKT activation in several in vitro models including MIA Pa-Ca2 (pancreatic cancer), KRAS G12C/Y96D NSCLC cells and the MGH1138-1 patient-derived model." (PMID 35251972, 2022). "In this study, we screened the inhibitory effects of the MEK inhibitor trametinib and BET inhibitor JQ1 on 7 different pancreatic cancer KRAS mutant cell lines." (PMID 35468095, 2022). "Studies found that the mutant version of KRAS was presented in 90% of pancreatic cancers, and up to 40% of colorectal cancers." (PMID 36619305, 2022). "More recently, Wang’s group used a multidisciplinary approach to identify the “non-signaling open conformation” existing in KRAS–GTP hydrolysis as a potential target for the treatment of KRAS-dependent non-small-cell lung cancer and pancreatic cancer." (PMID 36291766, 2022). "For example, U0126 effectively controls pancreatic cancer cell line proliferation via targeting the downstream effectors of KRAS signaling in a zebrafish xenotransplantation model." (PMID 36091807, 2022). "In the inducible KRAS pancreatic cancer mouse model (Ptf1-Cre; Rosa26-rtTa; TetO-KrasG12D), it has been described that pancreatic tumor cells regulate PSCs non-cell autonomously by secreting factors including Sonic hedgehog (SHH)." (PMID 35159011, 2022). "Treatment with KC-conditioned media on CAFs induces secretion of CXCL1, CXCL5, and CXCL7 greater than treatment with conditioned media from KRAS wild-type pancreatic cancer cells." (PMID 35159011, 2022). "Patients with high expression levels of both SEMA3C and KRAS had shorter survival times compared to those with high levels of either alone in pancreatic cancer patients." (PMID 35785187, 2022). "KRAS has been extensively studied in pancreatic cancer, and almost all studies pointed out its importance in the development of pancreatic cancer." (PMID 36358856, 2022). "Aside from V600E, the rate of BRAF in-frame deletions with KRAS WT pancreatic cancer is shown to be 4.21%." (PMID 35804932, 2022). "Active mutations in KRAS and BRAF, therefore, ultimately lead to the triggering of the MAPK signaling pathway, which is critical for the pancreatic cancer development." (PMID 36556296, 2022). "Carcinoembryonic antigen (CEA) is also a valuable target for adoptive cell therapy, as this glycoprotein family is expressed in nearly 75% of pancreatic cancers, and its upregulation is correlated with KRAS-driven metastatic CRC." (PMID 35014625, 2022). "Not only as the trigger of carcinogenesis, but the inception of mutant KRAS signaling also orchestrates a complex network of immunosuppression by manipulating the tumor microenvironment (TME) in pancreatic cancer." (PMID 36186449, 2022). "Meanwhile, the TCGA and ICGC databases were employed to analyse the function of KRAS G12V in pancreatic cancer." (PMID 34255132, 2022). "KRAS-enhanced macropinocytosis and reduced FcRn-mediated recycling make pancreatic cancer cells sensitive to albumin-conjugated drugs, such that the drugs are more likely to accumulate in cancer cells." (PMID 36046825, 2022). "A study revealed that ferroptotic pancreatic cancer cells carry KRAS protein to macrophages, resulting in the M2 polarization of macrophages." (PMID 35818358, 2022). "In fact, in pancreatic tumor cells, the ERK pathway which is continuously activated by KRAS mutations, confers resistance against apoptosis and regulates the progression of these cells in the cell cycle." (PMID 35883626, 2022).